HSF1 (heat shock transcription factor 1)
Diseases named in the same sentence as HSF1 in open-access papers (continued):
Sharing a sentence is not in itself a finding about the gene and the disease.
cancer (continued). "In the lymph node metastatic tissues, we observed strong IHC staining of p‐HSF1 and one of the downstream targets, HSP70, which has been implicated in carcinogenesis and the progression of various types of cancers." (PMID 28783244, 2017). "EMSA analysis shows increased HSF-1 DNA binding activity in unstressed cells due to the prominent nuclear localization of HSF-1 in carcinoma cells." (PMID 29348836, 2017). "We have shown that IER5 is required for the anchorage-independent growth of cancer cells and is an activator of HSF1." (PMID 26754925, 2016). "With a quantitative understanding of how Hsf1 is regulated when it is functioning properly, we can begin to unravel how it breaks down in neurodegenerative disorders and is usurped in cancer." (PMID 27831465, 2016). "Although HSP90 inhibitors offer promise for cancer cell treatment, resistance emerges early due to compensatory mechanisms involving activation of HSF1, which attenuates drug effectiveness." (PMID 27449291, 2016). "Several studies have proved that targeting HSR by inhibition of HSP72, HSP27 or HSF-1 can sensitize cancer cells to HSP90 and proteasome inhibitors." (PMID 27105490, 2016). "Silencing of either Hsp70 or HSF1 dramatically increased cancer cell sensitivity to Hsp90 inhibition and induction of apoptosis." (PMID 26743233, 2016). "Recently, pathological roles for HSF1 in cancer have been detailed, but in these capacitiesHSF1 still supports cell survival." (PMID 26952214, 2016). "HSF1 induces the transcription of Hsp70, Hsp27 and to some degree Hsp90 itself to protect cancer cells from apoptosis." (PMID 26743233, 2016). "We also have shown that mRNA expression of IER5 and HSF1 target genes show high correlation in several cancers." (PMID 26754925, 2016). "Our results thus add further evidence that HSF1 enhances tumorigenicity in multiple types of cancer." (PMID 27997575, 2016). "HSF1 is constitutively activated in cancer tissues and higher HSF1 activity is related to poorer prognosis of cancer patients." (PMID 26754925, 2016). "Heat shock factor 1 (HSF1) is a transcription factor that plays key roles in cancer, including providing a mechanism for cell survival under proteotoxic stress." (PMID 27746890, 2016). "The proteotoxic stress-responsive transcription factor HSF1 is frequently overexpressed in a variety of cancers and is vital to cellular proliferation and invasion in some cancers." (PMID 27997575, 2016). "Cancer cells seem to “hijack” HSF1 and utilize its transcriptional activity and central role in homeostasis to promote their growth and metastatic potential." (PMID 27713164, 2016). "It was reported that HSPs and heat shock factor-1 (HSF1) have essential roles in tumor initiation of cancer." (PMID 26751205, 2016). "Heat shock transcription factor 1 (HSF1), a key regulator of the heat-shock response, is deregulated in many cancers." (PMID 27713164, 2016). "A high-throughput phenotypic screen was conducted to find inhibitors of the HSF1-stress pathway in cancer cells and a hit compound based on a di-substituted 4,6-pyrimidine scaffold was discovered." (PMID 27746890, 2016). "Theses results show that HSF1 activation downstream of IER5 is important for proliferation of cancer cells." (PMID 26754925, 2016). "Activation of HSF1 plays a vital role in human physiology and ageing, as well as in pathological processes such as cardiovascular disease, neurodegeneration, and cancer." (PMID 27354066, 2016). "Since HSF1 activation supports malignant transformation, this approach holds promise for targeting HSF1 for cancer treatment." (PMID 27354066, 2016). "We analyzed data from The Cancer Genome Atlas (TCGA) database to compare HSF1 levels across multiple cancer types." (PMID 27997575, 2016). "Enhanced expression of IER5 induces abnormal HSF1 activation in cancer cells and contributes to the proliferation of these cells under stressed conditions." (PMID 26754925, 2016).
cancer (continued). "It has also been determined that the HSF1 program supports the malignancy of cancer in a variety of ways, including direct effects on the cell cycle, DNA repair, anabolic metabolism, and proliferation." (PMID 26511079, 2015). "Genes previously identified as an HSF1-regulated cancer-specific transcriptional program were also downregulated (FDR q-value = 0.042; normalized enrichment score (NES) 1.57)." (PMID 26327695, 2015). "The range and magnitude of changes in Hsp90 and Hsp27 as well as the specificity of the response raise the possibility that decreases in microtubule dynamics leads to an HSF1-dependent change in gene transcription, akin to that observed in cancer cells." (PMID 26320184, 2015). "In cancer cells, translation is driven by HSF1 through regulation of ribosome biogenesis, and HSF1-dependent transactivation is regulated by mTOR activity." (PMID 26473447, 2015). "HSPs induction in cancer cells is triggered by the transcription factor HSF1 that binds to unique DNA sequence motifs known as heat shock elements (HSEs) in the promoters of HSPs, inducing their transcription." (PMID 25954247, 2015). "We also find that Hsp70 does not respond to mutations in APC or inhibition of microtubule dynamics, suggesting this response is more akin to the Hsf1-mediated cancer program than a canonical heat shock program." (PMID 26320184, 2015). "Mendillo and colleagues showed that in cancer cells, Hsf1 targets promoters that are distinct from those it binds to after heat shock." (PMID 26320184, 2015). "HSF1 drives a transcriptional program in stromal cells that complements but is completely different from the program it drives in adjacent cancer cells." (PMID 26511079, 2015). "These patterns support our in vitro findings that Hsf1 drives the increases in HSPs observed in normal cells carrying a single mutation in APC and that these changes are preserved during cancer progression." (PMID 26320184, 2015). "The action of a monoallelic mutation of APC to induce global changes in otherwise normal cells raises the possibility that HSF1-mediated changes act early in cancer onset." (PMID 26320184, 2015). "Despite the well-characterized role of HSF1 in cancer development and progression, in the context of PKCθ activation and the inhibition of the insulin pathway, non-heat-shock HSF1 activation appears to provide a therapeutic advantage." (PMID 26298773, 2015). "The key sensor in the HSR, Hsf1, has recently been shown to regulate in malignant cancer cells a transcriptional program that is distinct from the program induced by HS." (PMID 26314864, 2015). "Unfortunately, HSF1 is also found to be over-expressed in a large number of cancers where it promotes a cancer-specific transcription program." (PMID 26517842, 2015). "HSF1 has also been implicated in malignant transformation, cancer cell survival, and tumor metastasis, but the precise mechanisms by which HSF1 promotes cancer progression remain poorly understood." (PMID 25537516, 2015). "HSF1 was also found to be constitutively activated in cancer tissues, modulating several cell cycle- and apoptosis-related pathways via its target genes." (PMID 25759792, 2015). "Recent work has revealed that HSF1, and by extension its network of regulated genes, plays a critical role in cancer onset and progression." (PMID 26320184, 2015). "The distinct roles of HSF1 in specific cancers suggest that its targets vary depending on the genetic context of the cell." (PMID 26320184, 2015). "The relationship between Hsf1 and cancer initiation led us to examine the behavior of Hsf1 in intestinal epithelial cells in APCMin/+ animals." (PMID 26320184, 2015). "Down-regulation of HSF1 in cancer cells correlates with an elevated apoptotic index, reduced cell proliferation and tumor growth in vivo." (PMID 24467529, 2014).
cancer (continued). "Many cancers histologically exhibit activated HSF-1 and increased HSP levels, and activate oncogenes to regulate cell proliferation and cell motility." (PMID 24930499, 2014). "HSF-1 expression is elevated in various cancers, including human prostate carcinoma cell lines, and has been shown to support proliferation of several cancer cell lines." (PMID 24930499, 2014). "Recent studies have indicated that HSF-1 is a key determinant in cancer progression and increased HSF-1 expression promotes HCC tumor invasion and metastasis." (PMID 24923353, 2014). "Functions of HSF1 in cancer are connected with HSPs’ activity, which generally protects cells from apoptosis, but also are independent of its classical targets." (PMID 24467529, 2014). "Overexpression of HSPs, which are the major targets of HSF1, was found in some tumors and in numerous cancer cell lines grown in vitro." (PMID 24467529, 2014). "In cancer cells, HSF1 drives a transcriptional program distinct from heat shock to promote metastasis and cell survival." (PMID 24800749, 2014). "Here in the present study, we report the anti-cancer activity of this HSF1 aptamer in cultured human cells." (PMID 24800749, 2014). "Considering its crucial role in many different processes important for malignant transformation and sensitivity of cancer cells, HSF1 appears an attractive and potent target for future anticancer strategies." (PMID 24467529, 2014). "Like Hsp90, Hsf1 is itself a key permissive factor in cancer progression and overexpressed in certain aggressive cancers (e.g. hepatocellular carcinoma)." (PMID 24970820, 2014). "HSF1 can modify the resistance of cancer cells to drugs increasing their efflux by ABC transporters." (PMID 24467529, 2014). "While this observation suggests an indirect role of HSF1 in cancer progression, a direct impact of HSF1 on malignancy has been discovered recently." (PMID 24800749, 2014). "The amazing transcriptional modification capabilities of HSF1 have also recently been demonstrated by its complete rewiring of the transcriptome in cancer." (PMID 25027850, 2014). "Significance: A problem with most of the Hsp90 inhibitor drugs now in cancer clinic trials is that they potently activate Hsf1." (PMID 24970820, 2014). "Further study will be critical in determining the role and regulation of neogenin-1 in various cancer types, as well as the roles of neogenin-1, galectin-3 and HSF-1 regulation in cancer metastasis." (PMID 24930499, 2014). "The majority of data on cancer-related potential of HSF1 comes from studies on Hsf1-/- MEFs and mouse models of tumorigenesis." (PMID 24467529, 2014). "Because HSP90 is co-regulated by HSF1 and is important for cancer cell growth, we further compared the inhibitory effects of iaRNAHSF1 against a potent Hsp90 inhibitor 17-(Allylamino)-17-demethoxygeldanamycin (17-AAG) on colony formation in soft agar." (PMID 24800749, 2014). "Cancer cells express high levels of molecular chaperones and pirate the protective functions of HSF1 to support their transformation." (PMID 25138053, 2014). "In highly tumorigenic cells HSF1 regulates several cancer-specific genes, which are different from genes activated during the heat shock response." (PMID 24467529, 2014). "Elevated expression of HSPs frequently observed in cancer cells apparently contributes to specific HSF1-related features of tumor phenotype." (PMID 24467529, 2014). "Based on this observation, the HSF1-cancer signature of 456 genes was established and its correlation with poor outcomes in diverse human cancers was determined." (PMID 24467529, 2014). "Based on these observations it was concluded that HSF1 supports cancer initiation and growth, although an exact mechanism on how it is achieved remains elusive." (PMID 24467529, 2014).
cancer (continued). "HSF1 depletion only minimally impacts normal cell viability, whereas cancer cells are strongly affected by HSF1 depletion." (PMID 24576043, 2014). "The first strategy was unsuccessful since celastrol treatment increased HSP70 in all 7 of the cancer cell types tested, this result related to HSF1 activation." (PMID 24589236, 2014). "In cancer cells, HSF1 drives a distinct transcriptional program from the classical HSR, implying a more complex function than previously anticipated." (PMID 25406061, 2014). "One possible reason for this is that treatment of cancer cell lines with HSP90 inhibitors generally leads to significant activation of HSF1 and up-regulation of HSP70; indeed, up-regulation of HSP70 is a key biomarker for the inhibition of HSP90." (PMID 24252366, 2013). "HSF1 is elevated and becomes activated in a wide range of cancers, its expression is coupled to the severity of disease, and it has been shown to be coupled to upstream signaling pathways in the malignant cell." (PMID 24278769, 2013). "In this study, we observed that HSF1 knockdown combined with HSP90 inhibitors led to striking inhibitory effects on cancer cell proliferation in vitro and tumor growth in vivo." (PMID 23615731, 2013). "When shRNA expression was induced by Doxycycline, robust HSF1 knockdown was achieved in all three cancer cell lines." (PMID 23615731, 2013). "HSF1 knockdown further enhanced the apoptotic proportion of cancer cells under HSP90 inhibitor treatment." (PMID 23615731, 2013). "Cancer cells in particular display higher levels of molecular chaperones and pirate the protective functions of HSF1 to support their transformation." (PMID 23874968, 2013). "A striking combinational effect was observed when HSF1 knockdown plus with HSP90 inhibitors treatment in various cancer cell lines and tumor mouse models." (PMID 23615731, 2013). "The role of HSF1 in carcinogenesis includes protecting cancer cells from programmed cell death, overriding cell cycle checkpoints and enhancing metastasis." (PMID 24165036, 2013). "Recent work has shown that, in malignant tumors, HSF1 is responsible for the orchestration of a transcriptional program, termed the HSF1 cancer program, which is distinct from the transcriptional response that is induced by heat shock." (PMID 24278719, 2012). "Another potential target is Heat shock factor 1 (HSF1), which is a transcription factor that stimulates synthesis of heat shock proteins and thus a promising target for cancer therapy." (PMID 25969759, 2012). "This program includes both HSF1 positively and negatively regulated genes and drives the expression of cancer-specific genes supporting oncogenic processes such as cell-cycle regulation, mitosis, energy metabolism, translation, cell signalling, and adhesion." (PMID 24278719, 2012). "HSF1 knockdown experiments in cancer cells demonstrate the interest of blocking this transcription factor in cancer therapy." (PMID 24212658, 2011). "Effective HSR is particularly important for survival of cancer cells, which are characterized by constitutively high levels of PS and coincident dependence on HSF1 activity." (PMID 21444945, 2011). "HSF1, in fact, plays a role in P-glycoprotein (P-gp) expression and activity, and incubation with quercetin prior to administration of anti-cancer drugs appears to be more effective at inhibiting MRP-mediated drug efflux and to enhance drugs‧ effectiveness." (PMID 24213118, 2011). "In this context, inhibitors of HSF1 and direct modulators of Hsp70 activity have been successfully tested as anti-cancer drugs, offering therapeutic benefits and selective effects on transformed versus untransformed cells." (PMID 24213118, 2011). "Blocking the actions of HSF-1 is now a hot topic in cancer biology due to the fact that malignant cells have a high dependency upon the activity of HSF-1." (PMID 27721330, 2011).
cancer (continued). "Altogether, HSF1 activity is hijacked in a pleiotropic manner by a large diversity of cancer cells and oncogenes to favor tumor initiation and progression." (PMID 24212658, 2011). "Although they can play a role indirectly by their ability to modulate HSF1, several works pointed out their regulatory role in cancer related genes." (PMID 24212658, 2011). "HSF1 has been involved in the etiology of cancer by its multiple effects in facilitating transformation and tumor invasiveness in response to diverse oncogenic stimuli." (PMID 24212658, 2011). "We also present an update on the compounds with potent HSF1-modulating activity of potential interest as anti-cancer therapeutic agents." (PMID 24212658, 2011). "It is noteworthy that HSF1 possesses additional properties in cancer, such as the enhancement of pro-malignant signaling pathways, involving PKA and TOR." (PMID 24212658, 2011). "Recently, an interesting anti-cancer approach has been developed based on the fact that HSF1 overexpression enhances the oncolytic effect of a replicative adenovirus." (PMID 24212658, 2011). "HSF1 is a primary regulator of the heat shock response and a factor in a number of human pathologies including cancer and neurodegenerative diseases." (PMID 21085490, 2010). "Our findings identify DHX8 as a critical regulator of stress-adaptive gene expression, highlighting its promise as a therapeutic target not only to disrupt HSF1-dependent transcriptional programs but also having broader effects in cancer cells under oncogenic stress." (PMID 41837178, 2026). "Since this seminal study, the role of HSF1 in the tumor microenvironment has been expanded to CAFs of breast, colon, and gastric cancers, where it regulates genes encoding ECM components to enhance cancer progression." (PMID 40457168, 2025). "This may be in part due to the high HSF1 copy number because a previous study showed that HSF1 expression has a greater dependency on MYC in non-cancer cells." (PMID 39831777, 2025). "They found that HSF1 is more active in advanced cancer, helping it grow and resist drugs." (PMID 41028522, 2025). "Several microRNAs (miRNAs) regulate the development of human cancers by influencing HSF1 activity." (PMID 40520012, 2025). "In cancer, ATF5 and HSF1, which are both involved in the UPRmt, have been linked to oncogenesis." (PMID 40680837, 2025). "In addition, the results of the current study support HSF1–MYC co-amplification as a potential biomarker for many cancer types and approximately one third of patients with HGSOC." (PMID 39831777, 2025). "Accumulating evidence indicates that HSF1 promotes tumor growth across multiple cancer types." (PMID 40520012, 2025). "By identifying precise changes in a patient’s cancer, such as issues with DNA repair, specific proteins like HSF1, ERs, and TOPK, or mechanisms by which the cancer evades the immune system, clinicians can select medications likely to be most effective for each individual." (PMID 41235005, 2025). "Thus, defining the role of HSF1 is essential for understanding cancer progression and developing novel cancer therapeutics." (PMID 41028522, 2025). "Importantly, the transcriptional programs of HSF1 in acute stress, cancer cells, and CAFs are distinct from one another." (PMID 40457168, 2025). "In summary, HSF1 clearly acts as a truly multifaceted player in cancer promotion." (PMID 40287736, 2025). "The MYC and HSF1 interaction will be the subject of future investigations, as this interaction is likely to be critical to tumorigenesis and perhaps several other functions known to be driven by MYC and HSF1, such as the cancer stem–like population among others." (PMID 39831777, 2025). "Combining indirect HSF1 inhibitors such as NXP800 with inhibitors of protein homeostasis pathways or standard cancer treatments could improve outcomes and help overcome resistance mechanisms." (PMID 40287736, 2025). "The role of HSF1 in cancer extends far beyond its classical function in stress response." (PMID 40520012, 2025).